INS (insulin)
Diseases named in the same sentence as INS in open-access papers (continued):
Sharing a sentence is not in itself a finding about the gene and the disease.
steatosis (continued). "In this review, we discuss the sites and mechanisms of insulin action and IR-related impairment along the spectrum of NAFLD, from simple steatosis to progressive NASH and cirrhosis." (PMID 33800465, 2021). "In a large cross-sectional study including 532 obese young individuals, it was shown that insulin clearance and the hepatic insulin resistance index calculated during an OGTT was ~50% lower in individuals with steatosis." (PMID 33498493, 2021). "As insulin sensitivity is strongly correlated with body weight, lower body weight of APP23 mice together with the lesser degree of steatosis potentially accounts for lower insulin levels in HFD-fed APP23 mice suggesting superior insulin sensitivity." (PMID 33864446, 2021). "Betatrophin was positively correlated to the age, waist circumference, total cholesterol, triglycerides, LDL cholesterol, glucose, insulin, HOMA-IR index and gamma glutamyl transpeptidase levels, and negatively correlated to the steatosis and NAS." (PMID 34203342, 2021). "In this review, we discuss the sites and mechanisms of insulin action and the IR-related impairment along the spectrum of NAFLD, from simple steatosis to progressive NASH and cirrhosis." (PMID 33800465, 2021). "Consistent with the improvement in the NAFIC score, serum ferritin and steatosis biomarkers, there were significant improvements in the ALT and AST levels after SGLT2i treatments and when compared to controls or insulin-based therapy." (PMID 33643221, 2020). "Furthermore, hepatic IL-6 has been shown to regulate glucose metabolism by increasing insulin sensitivity and negatively regulating hepatic glucose release to the periphery, maintaining liver tissue homeostasis and protecting against the progression of steatosis." (PMID 30818779, 2019). "As myocardial uptake of FFA is proportional to plasma concentration, the relative steatosis is likely to reflect a combination of increased FFA uptake, as well as a degree of impaired intracellular FA oxidation in the context of insulin resistance." (PMID 30464235, 2019). "The estimates and precision of measures of insulin, ALP, steatosis, NAS, presence of definite NASH, inflammation, fibrosis, and liver stiffness did not materially change." (PMID 31260026, 2019). "Despite improving leptin signaling in the hypothalamus and enhancing insulin sensitivity in HFD-fed mice, Lobe increased body weight and steatosis." (PMID 29979770, 2018). "A significant improvement in glycemic metabolism (insulin (p = 0.0001), fasting glucose levels (p = 0.006), HOMA-IR (p = 0.001), TyG index (p = 0.01)), in steatosis evaluation by the FL index (p = 0.0001) and TE values (p = 0.0001) has also been observed." (PMID 28805669, 2017). "T2DM zebrafish showed increased insulin release with VAT accumulation and hepatic steatosis, which suggests that zebrafish T2DM develops simultaneously and synergistically in multiple interacting organs." (PMID 28469250, 2017). "However, insulin sensitizers do not reverse fibrosis although it is associated with improved grade of steatosis, suggesting that insulin resistance might be necessary but not sufficient in the development of NAFLD." (PMID 28350839, 2017). "In addition, there was increased Nrf2 expression accompanied by low SOD1 expression in the liver, suggesting that HFFD may induce hepatic insulin resistance and subsequent steatosis through the enhancement of increased free fatty acid influx into the portal system and hepatic oxidative stress." (PMID 26265929, 2015). "Of the clinical parameters, the difference between study groups (normal liver, simple steatosis and NASH) in fasting insulin level at baseline was highly significant mainly due to high insulin level in the NASH group." (PMID 26420011, 2015). "Galbo and Shulman reported that feeding rats a high fat diet results in steatosis, increased intra-hepatic DAG content, and impairment of insulin stimulated PI3K signaling." (PMID 26438035, 2015).
steatosis (continued). "Insulin-resistant adipose tissue also produces excessive amounts of FFA via lipolysis creating a vicious cycle of accumulating lipotoxic metabolites, steatosis, and insulin resistance." (PMID 24830559, 2014). "Moreover, the WAT loss observed under MCD feeding may also reflect part of the pathomechanisms resulting in steatosis and NASH under severe calorie restriction and massive weight loss after bariatric surgery in addition to WAT mobilization seen in insulin-resistance states." (PMID 24594481, 2014). "Persons with steatosis had higher BMI, waist, DBP, TG, ALT, fasting and 2-hour insulin but lower HDL-C." (PMID 24732091, 2014). "The consumption of a diet containing low levels of n-3 PUFA for 3 months was sufficient to induce hepatic n-3 PUFA depletion in PLs, steatosis (despite the maintenance of VLDL secretion process) and insulin resistance." (PMID 21853118, 2011). "Participants diagnosed with steatosis were observed to be older and exhibited a higher incidence of metabolic abnormalities, including elevated HOMA, glucose, LDL cholesterol, triglycerides, and insulin, coupled with decreased HDL cholesterol." (PMID 40284193, 2025). "Compared with WT mice, Fgf15 Tg mice on HFD resisted weight gain, showed no signs of steatosis, and became more insulin sensitive." (PMID 40815899, 2025). "Using a murine model of steatosis and diabetes, they also demonstrated that genetic deletion of PAR2 (PAR2-KO) improved histological markers of steatosis activity and led to a reduction in plasma glucose and insulin levels." (PMID 40806209, 2025). "Patients with HC iron had lower serum insulin and HOMA-IR levels, suggesting that the development of steatosis among these patients might be secondary to cytotoxic injury from HC iron, uncovering a distinct phenotype of MASLD among these patients." (PMID 41264906, 2025). "Insulin promotes adipocyte differentiation and fatty acid uptake from circulating lipoproteins, while hypertriglyceridemia enhances FFA delivery to the liver and hepatic glucose production, leading to organ steatosis." (PMID 41300557, 2025). "Steatosis is most commonly induced by a combination of high carbohydrate levels (glucose with or without fructose), high levels of insulin and albumin‐conjugated free fatty acids (FFAs), typically oleic and palmitic acid." (PMID 41200938, 2025). "In addition to the presence of steatosis in PTENKO mice, these animals are hypoinsulinemic and have impaired HGO, as well as increased insulin sensitivity and glucose uptake in skeletal muscle." (PMID 40115165, 2025). "In this study we addressed the hypothesis that drivers of insulin clearance, such as CEACAM‐1 and IDE, would be reduced in obese horses and ponies with fasting HI and that these would present steatosis." (PMID 40476757, 2025). "However, resolving steatosis in hepatocyte Cul3 KO mice did not lead to overall metabolic improvement but caused liver pathology and systemic metabolic changes, including hepatic ceramide accumulation, elevated circulating fatty acid levels, and systemic insulin resistance." (PMID 40209947, 2025). "In mice fed a Western diet, chlorhexidine reduced weight gain, body fat, steatosis, and plasma insulin without changing caloric intake, while increasing colon triglycerides and proteins, suggesting reduced absorption of these nutrients." (PMID 38369624, 2024). "Furthermore, triglyceride and fasting glucose concentration as well as insulin and HOMA-IR were significantly higher in serum of patients with simple steatosis and MASH, respectively, when compared to controls." (PMID 38493749, 2024). "The justification for a preferred prescription of a mixture of probiotics is that different strains have achieved better outcomes in RCTs and can act on different targets, achieving better results in reducing steatosis, fibrosis, AST, ALT, serum lipids, glucose, and insulin." (PMID 38600992, 2024).
steatosis (continued). "Western blot analyses of insulin-induced AKT-serine phosphorylation showed that miR-149-5p-induced steatosis did not impair insulin signaling." (PMID 39263327, 2024). "We are unaware of published studies that have compared insulin sensitivity to glucose turnover between patients with biopsy-proven NASH and simple steatosis using the gold standard hyperinsulinemic euglycaemic clamp approach, and we therefore consider our results as novel information." (PMID 38901559, 2024). "Compared to CON, CAF increased body weight gain, plasma insulin, plasma glucose, decreased liver IRS‐1, AMPK mRNA expressions, and pancreatic β‐cell insulin immunoreactivity, and developed hepatocyte degeneration and microvesicular steatosis." (PMID 37970433, 2023). "Cumulatively, LL mice on HFD had higher blood cholesterol, liver triglycerides and microvesicular steatosis, whereas on HFHSD they had higher adipose pad mass but lower post-prandial glucose and insulin, raised blood cholesterol and raised liver lipogranulomas." (PMID 37031802, 2023). "In vitro, silencing of FGFR4 in primary mouse hepatocytes resulted in cell autonomous upregulation of IRS1, but not in an improvement of insulin signaling, which is likely mediated by a decrease in steatosis." (PMID 36586437, 2023). "Together, these data indicate that VitA mediates HFD feeding-induced steatosis by mechanisms that are independent of circulating insulin levels, although effects on modulation of insulin action in hepatocytes remain to be explored." (PMID 36891060, 2023). "This suggests that the nSMase2 translocation and the consequences it has on insulin signaling are not dependent upon steatosis per se." (PMID 37640282, 2023). "Strikingly, P-ERK levels were even higher within steatosis for HepG2 cells and steatosis with insulin stimulus for both proliferating HepaFH3 cells and HepG2 cells, while PHHs and confluent HepaFH3 cells were not responsive to insulin regarding ERK activation." (PMID 36009822, 2022). "It is therefore possible that patients with no or low-grade steatosis have a higher degree of hepatic insulin sensitivity, but a greater degree of beta cell dysfunction." (PMID 36336684, 2022). "A strong negative correlation between the MedDiet Score and ALT, insulin levels, fibrosis, and steatosis severity was evidenced in patients with NAFLD." (PMID 35057439, 2022). "Adiponectin augments insulin’s capacity to suppress glucose production, prevents hepatic DNL, suppresses FA synthesis in hepatocytes, and enhances FA β-oxidation, overall protecting the liver from steatosis." (PMID 36009862, 2022). "The linear regression analysis of the baseline conditions documented that the size of the liver positively correlated with body weight, BMI, neck and waist circumferences, waist to height ratio (WhtR), insulin and HOMA Index, fat mass and visceral fat, and steatosis grade." (PMID 35628889, 2022). "The clear differences in insulin sensitivity, observed in our study, between patients with medium-to-high grade steatosis and patients with no or low-grade steatosis, are comparable with a study by Lomonaco and colleagues." (PMID 36336684, 2022). "Our results suggest that anthocyanins modify lipid metabolism and rescue the OLZ-induced steatosis but do not influence insulin impairment induced by OLZ in skeletal muscle." (PMID 34684731, 2021). "Levels of BMI, HOMA-IR, fasting glucose, fasting insulin, triglycerides and cholesterol were significantly higher in patients with steatosis than those without steatosis, but levels of ALT, AST and HBV-DNA were significantly lower in patients with steatosis." (PMID 34440963, 2021). "By contrast, at least a part of the steatosis observed in the HFD control group may be due to increased de novo lipogenesis because SREBF1 is significantly activated, and insulin, the transcriptional inducer of Srebp1c, is elevated." (PMID 34444996, 2021).
steatosis (continued). "The presence of steatosis was not related to blood glucose, insulin, HbA1c, and HOMA-IR levels in the pre-treatment." (PMID 34136497, 2021). "This suggests that the mechanism of steatosis reduction or its inhibition by thiamine does not involve insulin sensitization and/or regulation of AMPK signaling on a transcriptional level." (PMID 33608323, 2021). "At clinically relevant plasma concentrations, metformin significantly ameliorated steatosis and improved insulin sensitivity in mice with GP73-induced non-obese NAFLD." (PMID 34853313, 2021). "Together, these studies have demonstrated that increased ChREBP activity improves insulin sensitivity by promoting simple steatosis without lipotoxicity." (PMID 32660130, 2020). "Serum insulin level was not statistically different over different grades of steatosis (F = 1.390, P = 0.252)." (PMID 32728230, 2020). "We speculate that the increased levels of pro-lipogenic factors, insulin, and glucose in DKO animals contributed to the exaggerated steatosis by activating highly responsive transcription factors, SREBP-1c and ChREBP." (PMID 32796650, 2020). "Compared to high trans-fat diets without additional fructose, these mice showed increased body weight and reduced insulin sensitivity, whereas no alterations in the degree of steatosis or liver transaminase levels were observed." (PMID 32046285, 2020). "In this study, it was also reported that salivary insulin concentration tended to be higher in obese patients with steatosis than in those without and that increased in parallel with the number of MetS elements." (PMID 31428049, 2019). "After adjusting for age, sex, BMI, fat mass, and insulin, osteocalcin concentrations were not related to portal inflammation, high grade of steatosis, fibrosis, or lobular inflammation." (PMID 32063885, 2019). "Collectively, these findings suggest that the hepatic change associated with simple steatosis, rather than NAFLD progression causes these alterations in the expressions of insulin signaling molecules and insulin-target enzymes." (PMID 29717275, 2018). "Although in this study control of acromegaly was reached by about 58% of patients, quite in line with data in the literature, we found a significant improvement in both steatosis and insulin sensitivity, regardless of hormonal levels." (PMID 30662461, 2018). "In conclusion, our results suggest that both metformin and calcium-vitamin D3 provide similar hepatoprotective effects in an insulin and AMPK-independent manner, with slightly additional protective benefits of their combination on the steatosis scores and hepatic cholesterol content." (PMID 29670844, 2018). "In the present study, FBG and serum insulin levels were strongly correlated with lobular inflammation and ballooning, rather than with steatosis grade." (PMID 29749571, 2018). "The studies on adults population have suggested that iron overload plays a significant role in pathogenesis of NAFLD and progression from simple steatosis to nonalcoholic steatohepatitis (NASH) through increasing oxidative stress and altering insulin signaling and lipid metabolism." (PMID 29854715, 2018). "Second, we did not collect specific data on steatosis, insulin levels or NASH and hence are limited in fully evaluating their implication in liver fibrosis." (PMID 28362068, 2017). "This is consistent with high ChREBP expression in the liver increases hepatic lipogenic gene expression and steatosis without impairing insulin sensitivity." (PMID 27098609, 2016). "Among these, it has been suggested that oxidative stress may have a role through reactive oxygen species inducing mutagenesis and both insulin resistance and lipid metabolic alterations are considered hepato-carcinogenic factors in HCV-related steatosis." (PMID 27231906, 2016).
steatosis (continued). "Overall, the majority of the studies evaluated the role of steatosis without considering insulin resistance or vice versa, due to the overlapping conditions, thus their independent role in the progression of liver fibrosis has not yet been adequately assessed." (PMID 27231906, 2016). "Recent studies, however, suggest that acute inhibition of Vanin-1 activity in Zucker Diabetic Fatty rats did not change the degree of steatosis nor did it affect insulin sensitivity or glucose production." (PMID 27667588, 2016). "Given the context of reduced insulin stimulation of lipogenesis but raised plasma lipid levels and increased hepatic FFA uptake, it would be expected that periportal cells to show the most severe steatosis." (PMID 27632189, 2016). "In addition, skeletal muscle is another important insulin-responsive tissue besides liver, and a very strong relationship between IR in T2DM and both skeletal muscle steatosis and non-alcoholic fatty liver disease has been reported." (PMID 26003803, 2015). "This alteration in insulin sensitivity may have been partially compensated for by increased levels of liver IRS2, protecting from further liver lipid accumulation and steatosis." (PMID 25402228, 2014). "When considered together, the data from our two in vivo mouse models indicate that either high or low insulin levels lead to steatosis, while normoinsulinemic mice do not develop excessive liver lipid accumulation." (PMID 22745692, 2012). "Thus, IRS expression was again assessed in cell culture model of steatosis and increased IRS-2 mRNA levels were found at low insulin concentrations, while our highest insulin condition resulted in increased IRS-1 mRNA." (PMID 22745692, 2012). "It is therefore likely that reduced steatosis and adipocyte macrophage infiltration plus altered WAT signaling all contributed to the improved metabolic profiles of the Het GIP Tg mice on the HF diet, including the improved insulin sensitivity." (PMID 22802954, 2012). "In fact, incubation of hepatocytes with GLP-1 and exendin-4 in the absence of insulin directly reduces Srebp-1c, and reduces hepatocyte steatosis." (PMID 23133675, 2012). "As most patients with NAFLD are obese and often resistant to insulin, steatosis can lead to significant co-morbidity or progress to non-alcoholic steatohepatitis, thus justifying therapeutic intervention already at the early stages." (PMID 22969728, 2012). "With 95% confidence intervals, lanifibranor has shown potential in improving both metabolic and hepatic health in MASLD via significant improvements in triglycerides, HDL cholesterol, insulin levels, and steatosis, regardless of the diabetes status of the patient." (PMID 39768147, 2024). "The VLDL-TG secretion rate in the fasting state and after insulin infusion is higher in obese individuals with steatosis (average TG of 11–23%) than in nonsteatotic individuals, and there is a positive correlation between VLDL-TG or VLDL1-TG secretion rate and hepatic TG content." (PMID 37591342, 2023). "In addition, we did not observe any significant difference for the glucose and insulin levels between the different steatosis groups." (PMID 35128832, 2022). "Levels of fasting blood glucose, fasting insulin, triglycerides, cholesterol, alanine-aminotransferase, aspartate-aminotransferase, HBV-DNA, body mass index, HOMA-IR and pathological changes in the liver with inflammation, steatosis were examined in all patients." (PMID 34440963, 2021). "Liraglutide significantly ameliorated steatosis, inflammation, and hepatocyte ballooning of non-tumorous lesions in the liver compared with the control findings, and insulin-positive β-cells were observed in the pancreas in liraglutide-treated mice but not in control mice." (PMID 32785012, 2020). "However, all were limited to the glycemic-steatosis paradox, while failing to realize that, except of glycemic control, response to insulin is essentially the rule in T2D, rather than the exception." (PMID 32128655, 2020).